RNU6-942P (RNA, U6 small nuclear 942, pseudogene)
Gene: Small nuclear RNA gene on chromosome 2 (26,042,675 to 26,042,781, forward strand). Ensembl gene ENSG00000199872.
Homologues: Orthologues: chimpanzee U6 (100% identical), macaque U6 (88% identical), pig U6 (79% identical), pig U6 (75% identical). Paralogues in human: RNU6-1099P (85% identical), RNU6-11P (85% identical), RNU6-16P (85% identical), RNU6-37P (85% identical), RNU6-1 (84% identical), RNU6-144P (84% identical), RNU6-2 (84% identical), RNU6-222P (84% identical), RNU6-235P (84% identical), RNU6-39P (84% identical), RNU6-3P (84% identical), RNU6-480P (84% identical), and 1286 more.